IL6 (interleukin 6)
Diseases named in the same sentence as IL6 in open-access papers (continued):
Sharing a sentence is not in itself a finding about the gene and the disease.
viral infection (continued). "In certain murine viral diseases, IL-6 has a protective role and contributes to the resolution of the acute infection, but, in others, including SARS-CoV-2, elevated concentrations of IL-6 are associated with pulmonary lesions, acute respiratory failure, and mortality." (PMID 36233516, 2022). "Therefore, the number of CD3+ T cells and the level of IL-6 on hospital admission may serve as predictive factors for identifying patients with wild-type virus infection who will have severe disease." (PMID 35346253, 2022). "However, more evidence shows that the hyper-production of IL-6 during viral infection might enhance viral survival by the up-regulation of Th2 cell switch Th0 cells and IL-4 expression." (PMID 36290585, 2022). "IL-6-deficient mice failed to properly respond to viral infection, and the number of immunoglobulin A (IgA)-producing cells at their mucosae was greatly reduced, which demonstrated that IL-6 has an effect on mucosal immunity." (PMID 35334059, 2022). "Notably, current pathological studies have shown that the severe patients infected by SARS-CoV-2 generally have higher plasma levels of IL-2, IL-6, IL-10, TNF-α, IFN-γ,41,43–45 implying a high risk of the inflammatory-associated cytokine storm after viral infection." (PMID 33895786, 2021). "In the acute phase, both IL‐6 and IL‐10 were increased in the patient group compared to the healthy people group, possibly because IL‐6 is an important factor in inducing B cells to differentiate into plasma cells to produce antibodies upon virus infection, and IL‐10 has an anti‐inflammatory effect." (PMID 33590892, 2021). "In addition, excessive and uncontrolled production of TNF-α, IL-1β, IL-6, and other inflammatory cytokines by macrophages may result in serious systemic complications during viral infections such as tissue damage and septic shock." (PMID 34946051, 2021). "Importantly, IL-6 is also required for combating viral infections." (PMID 34063554, 2021). "In addition, the damage to endothelial cells after viral infection and/or activation of endothelium by pro-inflammatory cytokines, such as IL-1β, IL-6, IFN-γ, IL-8, and TNF-α induces platelets and monocyte aggregation in the vascular wall and expression of tissue factor (TF)." (PMID 33357215, 2020). "Given that production of IL-6 is a broad response to both trauma and immunological challenge, it is not surprising that it is elevated irrespective of whether CNS damage is sterile or induced by a bacterial or viral infection." (PMID 33409494, 2020). "Therefore, it is hypothesised that over-expression of IL-6 during certain viral infections potentially enhances virus endurance and/or exacerbation of disease pathogenesis." (PMID 32788852, 2020). "Therefore, the suppression of IL-6/STAT3 signaling by elevated SOCS3 induced by IAV might contribute to excessive production of IL-6 during the virus infection." (PMID 31474976, 2019). "Moreover, the induced expression of SOCS3 and IL-6 was examined in vitro after the virus infection." (PMID 31474976, 2019). "Further, prior studies indicate that there is marked up-regulation of IL-1β and IL-6 in hospitalized children with serious viral infections, such as H1N1 influenza, suggesting that IL-1β may be responsible for molecular reactions that lead to airway inflammation and increased disease severity." (PMID 31766400, 2019). "However, certain scenarios create disparity of IL-6 production that may be detrimental to the cellular immune response during viral infections." (PMID 31134045, 2019). "In addition to IFNs, pDC are also able to rapidly produce pro-inflammatory cytokines and chemokines upon viral infection; therefore we analyzed the secretion of the pro-inflammatory cytokines IL-6, TNF, and the chemokine IL-8 protein in the cell culture supernatants by ELISA." (PMID 30344524, 2018).
viral infection (continued). "In contrast to the viral infection, we could not detect any increased mRNA expression of IL-6 in the BM or spleen of WT and IFN-γ-deficient mice with P. berghei XAT infection." (PMID 26991425, 2016). "The increased activity of IL-6 may influence the clinical symptoms, and increased IL-6 has been reported in saliva, serum and tears The break of T cells tolerance by viral infection leads to the activation of self-reactive T cells which by BAFF stimulate activation and maturation of B cells." (PMID 24985362, 2015). "Besides their ability to robustly and rapidly produce IFN, human pDCs produce proinflammatory cytokines, such as tumor necrosis factor α (TNF α) and interleukin 6 (IL-6), and secrete a list of chemokines to coordinate the attraction of various immune effectors in response to viral infection." (PMID 25077037, 2014). "Despite all of these limitations, elevated IL-6 serum levels may help to differentiate bacterial and viral infections, although serum levels of PCT, cortisol, and heparin-binding protein have been demonstrated to be of greater diagnostic value for community-acquired infections." (PMID 23690657, 2013). "To further evaluate whether TLR4 is involved in expression of cytokines induced by viral infection, we collected the supernatants from above transfected and viral infected cell cultures at 1 h p.i. or 4 h p.i. and measured expression of IL-6 and IFN- β by ELISA assays." (PMID 24278275, 2013). "It is possible that chorion cells contribute to the production of MDI factor containing IL-6 and TNF-α by amniochorion tissues in response to influenza virus infection and play a pivotal role in the pathogenesis of adverse pregnancy outcomes associated with the virus infection." (PMID 22899878, 2012). "Particular attention in this article is devoted to the role of cytokines (IL-6, TNF-α, and IFN-γ) in the pathogenesis of hyperacute viral infection." (PMID 42196581, 2026). "Previous studies have identified monocytes and macrophages as primary sources of IL-6, IL-10, and TNF-α during viral infections, while IL-8 is typically secreted by macrophages and endothelial cells." (PMID 41522679, 2026). "Among these, local inflammation of the olfactory epithelium following viral infection, with increased TNF-α production and IL-6 levels as regulators of apoptosis in olfactory epithelial cells, seems particularly important." (PMID 41602885, 2026). "This cellular activation leads to an earlier and amplified production of proinflammatory cytokines, such as IL‐6, TNF‐α, and IFN‐γ, which are mobilized to suppress viral infection." (PMID 41488232, 2026). "The IL-6, ZAP, and IFITM3 expression levels induced by MDV-dUS3 were also remarkably higher than that induced by wild-type virus infection." (PMID 40042340, 2025). "Accordingly, anti-inflammatory drugs that target IL-6 signaling, such as monoclonal antibodies and Janus kinase (JAK) inhibitors, have been explored in various viral infections." (PMID 40692679, 2025). "While the impact of these SNPs on IFN-α is less clear, IL-6 can influence the broader immune environment, potentially enhancing IFN-α responses in viral infections." (PMID 40881695, 2025). "It is widely acknowledged that during viral infection, the phosphorylation of STAT3, which is triggered by upstream activators such as interleukin-6 (IL-6), can exert an effective inhibitory effect on viral invasion." (PMID 41488475, 2025). "Next, we compared the top 10 upregulated cytokines/chemokines and found strong upregulation of IFNL2/3, IL-6, and IFNB1 in all animals with severe yellow fever." (PMID 40663406, 2025). "In the context of viral infections, IL-10 exerts anti-inflammatory via reducing the production of pro-inflammatory cytokines and chemokines, including TNF-α, IL-1β, IL-6, and IL-12, etc.." (PMID 41156600, 2025).
viral infection (continued). "Mechanistically, neurotropic viral infections such as PRV are known to activate the pathway, driving the transcription of pro-inflammatory cytokines (e.g., TNF-α, IL-6), while excessive ROS production further amplifies inflammation." (PMID 41180235, 2025). "Acute infection with CHIKV was characterized by higher concentrations of IP-10/CXCL10, IFN-α, IL-6, and TNF-α, all of which are well-established markers of viral infection and inflammation." (PMID 41346606, 2025). "The ability of C315R to upregulate IL-6 expression and enhance STAT3 phosphorylation aligns with previous studies on other viral infections." (PMID 40143240, 2025). "Elevated levels of IL-6, INF-g, TNF-a, and IL17a mark an exacerbated inflammatory response and reflect the body’s attempt to combat the viral infection, with IL-6 being a pivotal mediator of fever and acute phase reactions." (PMID 39203987, 2024). "From an immune standpoint, our results showed that the 2LPAPI medicine slightly increased the secretion of IL-6, IFN-γ, and IP-10—the three cytokines involved in the host immune responses against viral infections—in HPV16(L1)-treated PBMCs." (PMID 38611099, 2024). "IL-6 is critical for activation of CD4+ T-cells and Th2 responses during viral infections in humans." (PMID 39541407, 2024). "Nevertheless, expression of IL-6, TNF-α, and CCL-2 in the lung and brain increased with viral infection." (PMID 39077737, 2024). "IL-6 and TNF-α are key pro-inflammatory cytokines involved in the control of many viral infections, including WNV, but they also display an increase during WNND and appear as candidates for the cytokine-induced burden of illness." (PMID 38543749, 2024). "Following the influenza virus infection in the mice, significant increases in IL-6 and TNF-α concentrations in the serum indicated the activation of the immune system and the initiation of inflammatory responses to combat viral infection." (PMID 39410114, 2024). "Cytokines and inflammatory chemokines (IL-1ra, IL-6, TNF-α, IL-8, G-CSF, MCP-1/CCL2, and PDGF) have been shown to be elevated in the CSF samples of pediatric patients in whom viral infection led to the SIDS in comparison with the control groups." (PMID 38675861, 2024). "Following viral infection, for example, with CMV, immune cell-derived IL-6 was shown to stimulate glucocorticoid production in mice, reduce vasodilatation and prevent excessive inflammation." (PMID 39107476, 2024). "On the other hand, the model group showed a significant increase (p ≤ 0.001) in all three inflammatory factors after virus infection, with TNF-a, IL-6, and iNOS levels at 144.11 ± 1.92 pg/mL, 417.62 ± 6.46 pg/mL, and 5.14 ± 0.25 pg/mL, respectively." (PMID 38426086, 2024). "In chronic human viral infections like HIV and hepatitis B virus (HBV) or infections like lymphocytic choriomeningitis virus (LCMV), IL-6 signaling is crucial in controlling the viral activities." (PMID 38251210, 2024). "Cytokine disturbances, especially increases in IL-6 and TNF-α, are common in both mental illnesses and viral infections, but are very unspecific." (PMID 39206043, 2024). "For example, women, after a viral infection, have a different expression of ACE2 and TMPRSS2 receptors, lower production of proinflammatory interleukin-6, and increased activity of innate immune cells against pathogens." (PMID 38541228, 2024). "TNF-α, IL-6, and IL-1β play a critical role in various inflammatory diseases, while MCP-1 expression is correlated with the pathogenesis of certain diseases or viral infections." (PMID 38275672, 2024). "IL-6 is a major cytokine produced following TMEV and other viral infections and displays an anti-apoptotic function." (PMID 37153539, 2023). "The mRNA levels of IL-1β, IL-6, and IL-8 showed a trend of decreases and then increases, while the mRNA levels of TNF-α and IL-10 significantly increased after viral infection." (PMID 36995259, 2023).
viral infection (continued). "Among them, IL6/STAT3 signaling, an intrinsic antiviral and pro-inflammatory pathway, has been suggested to contribute to several viral disease progression." (PMID 37099596, 2023). "We found that virus-induced mRNA levels of key proinflammatory cytokines, IL6, IL1B, CCL2, and CXCL10, were decreased in monocytic cell lines, namely THP1 and U937, and in PBMCs treated with Senexin B prior to viral infection." (PMID 37376593, 2023). "Emodin was able to combat viral infection by regulating the levels of the cytokines TNF-α, IFN-γ, IL-6, and IL-4 in the sera of infected mice." (PMID 37764342, 2023). "Further, our intervention experiments show that the total leukocyte counts in BAL fluid and the expression of IL-6 and KC in the lung of mice are significantly decreased by BRD4 inhibitor JQ1 treatment during viral infection after CS exposure." (PMID 36721187, 2023). "Inflammatory cells, IL-6, KC and BRD4 were synergistically induced in the lung of mice by viral infection and CS exposure, and the former three were decreased by JQ1 (BRD4 inhibitor) treatment." (PMID 36721187, 2023). "Studies have shown that GDF15 is related to inflammatory cytokines, such as IL-6 and CRP, suggesting an essential role in maintaining inflammation throughout viral infections." (PMID 37408184, 2023). "Many viral infections, including HSV-1, RSV, and SARS-CoV-2 infection enhances the production of several cytokines, such as IL-6, IL-8, and TNF-a in epithelial cells." (PMID 37112969, 2023). "Interleukin 6 (IL6) is a potent inducer of the acute phase response and contributes to host defense during viral infection and tissue injury." (PMID 37175446, 2023). "Interleukin-6 (IL-6) is required for inflammatory reactions induced by TNF, IL-1, INF, and bacterial or viral infections." (PMID 37190141, 2023). "The mRNA expression levels of IL-6, IL-18, IFN-α, IFN-β, and ISG-15 in the peripheral blood mononuclear cells (PBMCs) were significantly up-regulated during viral infection." (PMID 37632087, 2023). "In contrast, a significant difference was found between both experimental groups for the expression of IL-6, IP10, and CXCL9 7 days after virus infection." (PMID 38143489, 2023). "Moreover, researchers have further proven that IL-6-mediated signalling, as a vital component of innate immunity and inflammation, could be negatively regulated by miRNAs at the post-transcriptional level during viral infection, such as rabies virus (RABV)." (PMID 37577373, 2023). "A possible classification of the main patterns of cytokines inflammatory mechanisms is based on the axes IL-6/CRP and IL18/Ferritin as infection programs related to bacterial and viral infections." (PMID 36385417, 2023). "We observed that type I IFNs suppressed IL-6 and macrophage-dependent MMP production following mucosal viral infection." (PMID 35512020, 2022). "We found that the expression of the common antiviral factor RIG-1, IFN-α, IL6, MXA, and IL1 in sh-RSAD2 cells was significantly inhibited after virus infection compared with sh-control cells." (PMID 36423196, 2022). "We detected tissue-specific chemokine and cytokine storms in response to viral infection, including well-defined biomarkers in severe SARS-CoV-2 and IAV infections such as CXCL10, IL-6, and IL-10." (PMID 35962146, 2022). "In response to most viral infections, B cells can bind to viral proteins through their antigen receptors, by secreting effector molecules (IL-2, IL-4, IL-6, IFN-γ, TNF-α) to help contain viral infections." (PMID 35774402, 2022). "While the axes IL-1β/IL-6 link to CRP production in bacterial infections, IL-18 production links to transferrin in viral infection." (PMID 35663992, 2022). "Acute viral infections of the upper aerodigestive tract induce various proinflammatory cytokines, including IFN-γ, IL-1β, and IL-6." (PMID 35915851, 2022). "The key genes IL6 and AGT are involved in regulating immune response, cytokine activity, and viral infection." (PMID 35165525, 2022).
viral infection (continued). "For instance, during the acute inflammatory response to a virus infection, the body releases the cytokines TNF-α, IL-1, and IL-6, which act on fibroblasts and endothelial cells, hence increasing vascular permeability." (PMID 35755996, 2022). "CCL5) that are known to respond to dsRNA, proinflammatory cytokines IL-6 and IL-8 that were shown to be suppressed by sEVs from TVV positive T. vaginalis, and IL-1β, a proinflammatory factor during viral infection." (PMID 35602021, 2022). "The increase in IL-1β, IL-6, IL-4, and TNF-α expression in the spleen indicates the activation of the immune system, resulting in resistance to virus and prevention of virus infection." (PMID 36177044, 2022). "In the acute inflammatory response phase to viral infection, an early increase in serum IL-1β and TNF-α levels are observed within the first 30 min, followed by a rise in IL-6 levels." (PMID 35888173, 2022). "Pro-inflammatory cytokines, such as IL-6, IL-1β, and TNF-α, are significantly increased during viral infections and exacerbate lung tissue damage." (PMID 36147321, 2022). "Collectively, NP in plasma should be a more sensitive biomarker for viral infection, including SARS-CoV-2, than CRP and IL-6." (PMID 35529699, 2022). "Pro-inflammatory cytokines, such as interleukin-6 (IL-6) and tumor necrosis factor-alpha (TNF-α) produced under viral infections, can exacerbate the severity of illness, resulting in poor prognosis, including cytokine storms." (PMID 35062284, 2022). "At the same time, IL-1β, IL-4, IL-6, IFN-γ, GM-CSF, and TNF-α activate inflammatory effector mechanisms typical of a viral infection." (PMID 34831403, 2021). "Even though the combination of viral infection and Cs exposure to mimic AECOPD in mice was previously reported, as far as we know, the coexistence of exacerbated levels of serum IL-6 and reduced mice survival is a very unique feature of our model." (PMID 34203121, 2021). "Here, we demonstrated that siBeclin1 can be used to increase the efficacy of antiretrovirals in decreasing viral infections and that siBeclin1 can also be used to reduce the secretion of inflammatory cytokines such as, MCP-1, IL-6, and RANTES in glial cells." (PMID 33561939, 2021). "Cytokine storm particularly of IL-6, IL-8, IFN-γ is responsible for hyperferritinemia in viral infections." (PMID 33988463, 2021). "The differential genes such as KITLG, FOXP3, miR-451, IL-2, IL-10, IL-6, and TNF-α are mainly involved in viral infection and the immune-inflammatory responses." (PMID 34867371, 2021). "Moreover, the inhibitory effects of baricitinib on interferon-gamma, which has a broad-spectrum antiviral activity at multiple stages, might result in a hypothetical negative impact when added to the analogous effects in the defense against viral infections of IL-6 blockade." (PMID 34820393, 2021). "Bacterial or viral infection activates NF-κB through toll-like receptors, resulting in the production of proinflammatory cytokines including TNF-α, IL-1β, and IL-6." (PMID 34393799, 2021). "Many bacterial diseases are characterized by elevated levels of circulating IL-1β and IL-6 with a concomitant increase in plasma CRP, while viral infections are commonly characterized by elevated levels of the pro-inflammatory cytokine IL-18." (PMID 35062248, 2021). "In addition, IL-6 suppression does not resolve all of the aspects of the multifaceted pathophysiology of COVID-19 pneumonia, including cell death, abnormal coagulation and lung inflammation caused by viral infection." (PMID 34501738, 2021). "We selected IFNB1, IL6, and CXCL8 as markers of host response, representative of overlapping transcriptional responses to viral infection." (PMID 34357881, 2021). "We found that CyPA, induced by virus infection via CD147 receptor, promotes inflammation by upregulating the expression of IL-17, IL-6, and IL-1β in lung epithelial cells." (PMID 34564690, 2021).